PFKFB3 (6-phosphofructo-2-kinase/fructose-2,6-biphosphatase 3)
Diseases named in the same sentence as PFKFB3 in open-access papers (continued):
Sharing a sentence is not in itself a finding about the gene and the disease.
tumor (continued). "It has been confirmed that PFKFB3 is upregulated in a variety of tumor cells, and inhibition of it results in suppression of the growth of tumor cells by downregulating the glycolytic flux." (PMID 28977989, 2017). "We here also explored the effects of PFKFB3 suppression on the cell cycle progression and tumor spheres formation, which was usually used to determine the stemness of cancer cells." (PMID 28061878, 2017). "Besides the close association of the oncogene of hematologic disease and PFKFB3 expression, ROS enrichment, as a product of mitochondrial electron transport chain, was considered to results in risk of genetic instability, and is subsequently at risk of developing resistant tumor cells." (PMID 28977989, 2017). "In particular, most glycolytic genes, including PFKFB3, are upregulated at the transcriptional level with respect to other pathways in central metabolism, thus supporting a higher dependence of tumor ECs on glucose metabolism." (PMID 29321777, 2017). "PFKFB3 has been suggested to play a crucial role in many types of tumor cells as well as various cells in the tumor microenvironment." (PMID 29263928, 2017). "The pharmacological inhibition of PFKFB3 via PFK15 suppressed tumor growth and alleviated metastasis in HNSCC, offering a promising strategy for cancer therapy." (PMID 28061878, 2017). "As a critical glycolysis regulator, the PFKFB3 gene/enzyme can influence cell cycle and tumor cell proliferation." (PMID 28977989, 2017). "By analysing the histoscores of PFKFB3 in both tumor and normal tissues, we observed a significantly higher expression of PFKFB3 in HNSCC tissues." (PMID 28061878, 2017). "Recent studies have also shown that the efficacy of PFKFB3 inhibition in tumor cells is not only related to glycolysis, but also autophagy." (PMID 28977989, 2017). "In both normoxic and hypoxic environments, PFKFB3 inhibition by compound or PFKFB3 gene knockdown decreases intracellular ROS dramatically and prevents the proliferation of tumor cells in vitro and in vivo." (PMID 28977989, 2017). "Since ECs’ lining tumor blood vessels have a much higher glycolytic rate than healthy ECs, they are more sensitive to PFKFB3 blockade." (PMID 28081641, 2017). "Based on the efficacy of the glycolysis flux regulation of PFKFB3, PFKFB3 inhibitors were expected to work in drug-resistant tumor cells, or at least to combine synergistically with conventional drugs." (PMID 28977989, 2017). "Instead, PFKFB3 inhibition enlarges the vessel lumen and stabilizes tumor vessels by increasing vessel maturation through pericyte recruitment." (PMID 28081641, 2017). "The role of PFK15 was also validated in HNSCC, the pharmacological inhibition of PFKFB3 result in suppression of tumor growth and alleviation of the lung metastasis in the xenograft mice models." (PMID 28977989, 2017). "In the isolated neoplasms, the mRNA levels of PFKFB3 were decreased to a greater extent at CT7 than at CT19." (PMID 27079271, 2016). "A small molecule inhibitor of PFKFB3, 3-(3-pyridinyl)-1-(4-pyridinyl)-2-propen-1-one (3PO), suppresses glycolytic flux and is cytostatic to tumor cells." (PMID 26918353, 2016). "PFKFB3 isozyme is constitutively expressed by tumor cells and required for the high glycolytic rate." (PMID 26918353, 2016). "Overexpression of the PFKFB3 enzyme leads to high glycolytic metabolism, which is required for cancer cells to survive in the harsh tumor microenvironment." (PMID 27669567, 2016). "In conclusion, this study supports the further pre-clinical testing of rational combinations of PFKFB3 inhibitors with autophagy inhibitors for toxicity and efficacy in tumor-bearing animals." (PMID 24451478, 2014). "In PFKFB3 knockout mice, tumor size and weight were significantly decreased as compared to control mice." (PMID 25250177, 2014). "PFKFB3 inhibitors effectively and specifically target tumor cells in vitro and decrease tumor burden in vivo." (PMID 24451478, 2014).
tumor (continued). "Another key glycolytic enzyme highly expressed in tumor cells is 6-phosphofructo-2-kinase/fructose-2,6-bisphosphatase isozyme 3 (PFKFB3), which generates fructose-2,6-bisphosphate (Fru-2,6-BP)." (PMID 23776707, 2013). "As a result of proper targeting, the PFKFB3 inhibitor reduced the Fru-2,6-BP level and glycolytic rate in cell, ultimately, leading to tumor growth inhibition and massive cell death." (PMID 21957443, 2011). "Several PFKFB3 inhibitors, such as 3-PO, which interferes with the catalytic activity of PFKFB3 and results in cytotoxicity, apoptosis, and growth inhibition in various types of tumor cells, have been discovered." (PMID 40612109, 2025). "PFKFB3 kinase inhibitor-based nanoplatforms normalized tumor vessels." (PMID 40235732, 2025). "Notably, the PFKFB3 inhibitor 3PO was shown to increase vessel integrity and enhance tumor perfusion, resulting in decreased hypoxia and increased drug delivery." (PMID 41235226, 2025). "High doses of 3-PO, a small molecule inhibitor of PFKFB3, can inhibit proliferation of cancer cells and reduce the growth of primary tumors, whereas a low dose of 3-PO induced tumor vascular barrier tightening and maturation, reducing cancer cell intravasation and metastasis." (PMID 40045411, 2025). "Furthermore, targeting PFKFB3 or CPT1a has been shown to result in a reduction of pathological angiogenesis as well as the normalisation of tumour vasculature, signifying a prospective novel therapeutic target for cancer therapy." (PMID 40268524, 2025). "PFKFB3 RNA expression varied with tumor subtype, indicating that a future inhibitory treatment may be more effective in the Luminal A and HER2 positive tumors than the in triple negative and Luminal B subtype." (PMID 40022029, 2025). "Importantly, the genetic or pharmacologic inhibition of PFKFB3 promoted tumor blood vessel normalization, a newer concept in adjuvant cancer therapy that aims to restore vessel perfusion and improve chemotherapy efficacy." (PMID 39567756, 2025). "PFKFB3 expression was found to be predominant in TAMs in CRC tumor samples." (PMID 41516095, 2025). "Moreover, as there are numerous reports of off-target effects associated with 3PO, further studies are needed to determine the safety and feasibility of targeting PFKFB3 in the context of tumor vascularization." (PMID 41235226, 2025). "Furthermore, tumor compartments exhibited a 3.8-fold higher PFKFB3 expression relative to matched stromal regions (65.94 ± 50.59 vs. 17.27 ± 17.50, p < 0.00001)." (PMID 41516095, 2025). "We hypothesized that the inhibition of PFKFB3 could reduce the inflammatory response in tumors and then inhibit tumor growth." (PMID 38779358, 2024). "PFKFB3 inhibitor in combination with DDP led to a remarkable reduction in tumor growth in vivo." (PMID 39295937, 2024). "A critical role for PFKFB3-driven glycolysis in regulating tumor growth was confirmed by our examination of a constitutive knockout mouse model of the Pfkfb3 gene where we found that PFKFB3 was required for oncogene-driven anchorage-independent growth in vitro and xenograft growth in vivo." (PMID 39001392, 2024). "In addition, it was reported that tumor-associated monocytes in HCC showed enhanced glycolysis, increased expression of the key glycolytic enzyme PFKFB3, and activation of the nuclear factor kappa B signaling pathway mediated the increased expression of PD-L1." (PMID 39086383, 2024). "Furthermore, PFKFB3 expression levels were found decreased in tumor tissues when 3PO was used alone or in combination with RT." (PMID 39007350, 2024). "Importantly, unlike conventional anti-HCC drugs that target individual pro-angiogenic drivers, PF-543 impairs the PFKFB3-dictated glycolytic energy engine that fuels tumor angiogenesis, representing a novel and potentially safer therapeutic strategy for HCC." (PMID 38200582, 2024).
tumor (continued). "Reducing the glycolysis of tumor endothelial cells by inhibiting the function of PFKFB3 inhibits their proliferation and thus normalizes the tumor vasculature as evidenced by regular TEC alignment, a dense tumor vascular barrier, and unobstructed blood perfusion." (PMID 38824197, 2024). "Targeting PFKFB3 in ECs normalizes tumor vascularity and significantly prevents metastasis." (PMID 39318551, 2024). "Interestingly, p38γ can participate in the glycolysis of tumor cells by stabilizing the expression of PFKFB3 protein." (PMID 39482755, 2024). "Recent in vivo experimental studies suggested that the reduction of tumor hypoxia by tumor vessel normalization (TVN), through the inhibition of the glycolytic activator PFKFB3, could significantly improve tumor response to therapy." (PMID 39007350, 2024). "further demonstrated the impact of PFKFB3 acetylation status on its activity, showing that acetylated PFKFB3 can significantly promote glycolysis and protect cells from cisplatin-induced apoptosis, revealing the potential role of PFKFB3 modification status in tumor resistance mechanisms." (PMID 39877360, 2024). "Increased PFKFB3 expression has been demonstrated in multiple tumor types." (PMID 39001392, 2024). "A high rate of glycolysis has been observed in pre-neoplastic tissue both in vitro and clinically, and although still preliminary, our studies indicate that PFKFB3 may play an important role in tumor initiation." (PMID 39001392, 2024). "As PFKFB3 is widely expressed in almost all types of tumor cells, the uptake ratios and the corresponding blocked uptake ratios indicated that the accumulation of radioactivity in cells is selective and could be mediated by PFKFB3." (PMID 37035116, 2023). "In addition, targeting the key glycolytic enzyme PFKFB3 decreases the growth and migration of ECs in vitro and normalizes abnormal tumor vessels in vivo." (PMID 36740704, 2023). "However, the PFKFB3 was inconsistent with high-throughput data which was downregulated in tumor tissue (logFC: −2.369, P < 0.05)." (PMID 37663298, 2023). "In addition, inhibition of PFKFB3 has been reported to disrupt pathological angiogenesis and induce normalization of tumor vasculature, thereby reducing metastasis and improving chemotherapy efficacy." (PMID 36990998, 2023). "Besides its glycolytic function, PFKFB3 is a crucial player in regulating endothelial cells, tumor angiogenesis, and tumor vascularization." (PMID 36768924, 2023). "As such, hypoxia could downregulate the expression of PFKFB3; by contrast, under normoxia, the upregulation of PFKFB3 in tumor cells was observed." (PMID 37476196, 2023). "Additionally, signals from tumor-delivered VEGF led to the upregulation of 6-phosphofructo-2-kinase/fructose-2,6-biphosphatase 3 (PFKFB3) in endothelial cells, activating PFK-1, further intensifying the glycolytic phenotype." (PMID 38071310, 2023). "PFKFB3 has been reported to play an important role in promoting tumor progression." (PMID 36990998, 2023). "Moreover, our results indicated that PFKFB3 promoted tumor growth through regulating G2/M cell cycle and involved in metastasis through EMT regulation in OSCC cells." (PMID 37919747, 2023). "Tumor cells were examined by Western blot assay to determine whether IL-6 knockout affects the role of sorafenib in regulating PFKFB3 and HIF-1α." (PMID 37476196, 2023). "Besides, the expression of PFKFB3 was reported to promote lymph node metastasis and increase the tumor node metastasis (TNM) stage." (PMID 36973739, 2023). "PFKFB3 regulates tumor proliferation, invasiveness, and migration through different mechanisms." (PMID 37253634, 2023). "PFKFB3-modulating glycolysis is essential for lymphotoxin α–promoted tumor angiogenesis in HNSCC." (PMID 37919747, 2023). "In addition, it has been reported that Pfkfb3 is required for the proliferation and survival of tumor cells, which are similar to stem cells in many ways." (PMID 38813509, 2023).
tumor (continued). "We found differences in PFKFB3 expression in tumor cells under normoxia and hypoxia." (PMID 37476196, 2023). "However, the systematic study of crosstalk between PFKFB3 and Tumor microenvironment (TME) in pan-cancer has less been examined." (PMID 37253634, 2023). "Therefore, targeting PFKFB3 of its effects on glycolysis of endothelial cells (ECs) during tumor angiogenesis has become a burgeoning research field in tumor therapy." (PMID 36187335, 2022). "PFKFB3-expressing monocyte-derived macrophages massively infiltrated tumor in colon." (PMID 36733385, 2022). "Thus, our findings revealed that tRiMetF31 is a novel component of the miR-34a tumor suppressor network and plays a pivotal role in mediating miR-34a-induced suppression in migration and angiogenesis via targeting PFKFB3." (PMID 35961977, 2022). "In addition, the PFKFB3 haplodeficiency or blockade induces tumor vessel normalization by tightening the EC barrier and promoting pericyte quiescence." (PMID 35681715, 2022). "We focus on the role of PFKFB3 in IECs to regulate the tumor microenvironment." (PMID 36016583, 2022). "PFKFB3 is a key enzyme in the glycolysis of endothelial cells and can mediate tumor progression." (PMID 36105288, 2022). "In addition, a SCLC xenograft model was used to evaluate the role of PFKFB3 in CSC mediated tumor growth in vivo." (PMID 35804016, 2022). "PFKFB3 regulated glucose metabolism in tumor cells through a variety of signaling pathways." (PMID 35094634, 2022). "PFKFB3 inhibition or haploinsufficiency normalize tumor vessel reducing glycolysis." (PMID 35681715, 2022). "Some studies revealed that inhibitors of autophagy could increase the anti-tumor effects of PFKFB3 inhibitors." (PMID 35887232, 2022). "The pathophysiological response of PFK158 was investigated to determine whether PFKFB3 perturbation affects CSCs induced tumor growth in vivo." (PMID 35804016, 2022). "We hypothesized that LINC00930 and PFKFB3 depletion in combination with radiotherapy might have a better anti-tumor effect." (PMID 35209949, 2022). "Moreover, PFKFB3 inhibition retards the growth of a tumor, an observation that is in line with the expression of autophagy amongst cancer cells." (PMID 36551290, 2022). "PFK158, a PFKFB3 inhibitor, was indicated to suppress the tumor development." (PMID 36016583, 2022). "Importantly, we found that phosphorylation of PFKFB3 S478 has a role in regulating BC glycolysis, cell proliferation, migration, drug resistance, and tumor formation." (PMID 33931981, 2021). "PFKFB3 is an autophagy substrate and an elevated level of PFKFB3 when autophagy is impaired may explain the induced tumor recurrence." (PMID 34829881, 2021). "PFKFB3 is a primary enzyme responsible for glycolytic tumor metabolic reprogramming." (PMID 34831136, 2021). "However, PFKFB3 inhibition has been shown to decrease tumor formation in Tsc1- and Tsc2-null tumors implanted in a mouse model as well as diminishing the cellular proliferation and colony formation in vitro." (PMID 34831136, 2021). "PFKFB3, a crucial regulator of glycolysis, shows great importance in tumor development." (PMID 33931981, 2021). "In addition, SRC is known to promote tumor progression and glycolysis by regulating PFKFB3 activity 36-38." (PMID 33664855, 2021). "Our study demonstrates that PIM2 mediates PFKFB3 phosphorylation thus regulates glycolysis and paclitaxel resistance to promote tumor progression in BC and provides preclinical evidence for targeting PFKFB3 as a new strategy in BC treatment to battle paclitaxel resistance." (PMID 33931981, 2021). "PFKFB3 inhibition with 3PO was also observed to decrease tumor metastasis." (PMID 34831136, 2021). "Computational analysis demonstrated that a novel tumor suppressor, 3-(3-pyridinyl)-1-(4-pyridinyl)-2-propen-1-one (3PO), can competitively inhibit PFKFB3, and decreases intracellular concentrations of fructose 2,6-bisphosphate; this subsequently decreases glycolytic flux in various tumor models." (PMID 33883040, 2021).
tumor (continued). "The inhibition of PFKFB3 may play a positive role in the normalization of tumor vessels so that it helps to reduce tumor metastasis and improve the effect of chemo- and immunotherapy." (PMID 33777937, 2021). "Here, we comprehensively describe the discoveries and observations to date related to the genetic basis, regulation of expression, and protein structure of PFKFB3/4 and discuss the functional involvement in tumor progression, metastasis, angiogenesis, and autophagy." (PMID 33671514, 2021). "Indeed, inhibition of PFKFB3 reduced pathological angiogenesis, induced tumor vessel normalization, downregulated glycolytic activity in pericytes, tightened the EC barrier, impaired metastasis and improved chemotherapy." (PMID 33430906, 2021). "Therefore, we analyzed the possibility of inhibiting tumor and endothelial cell metabolism through the inhibition of PFKFB3 by a small molecule, (E)-1-(pyridin-4-yl)-3-(quinolin-2-yl)prop-2-en-1-one (PFK15), as a promising therapy." (PMID 33922320, 2021). "Research has proposed that PFKFB3 is highly expressed in a large number of malignant tumor cells." (PMID 34612136, 2021). "Moreover, inhibition of the glycolytic activator PFKFB3 (6-phosphofructo-2-kinase/fructose-2,6-bisphosphatase 3) proved to be effective in inducing tumor vessel normalization, reducing metastasis and improving chemotherapy." (PMID 34201298, 2021). "Previous study showed that KDM2A and PFKFB3 promoted angiogenesis in various tumor cells." (PMID 34079757, 2021). "Notably, pharmacological inhibition of tumour-cell-specific cyclooxygenase (COX)-2 leads to reduced expression of VEGF and, consequently, of PFKFB3, the gene that encodes 6-phosphofructo-2-kinase/fructose-2,6-biphosphatase 3, in the TECs." (PMID 33828258, 2021). "To further examine the effect of lncRNA H19 on tumor progression and the PFKFB3 gene-mediated glycolysis pathway in vivo, we established a nude mouse transplanted tumor model and used shRNAH19-1720 (named sh-H19) to knockdown the expression of lncRNA H19 in oral CAFs." (PMID 33762576, 2021). "Furthermore, the deletion of glycolytic genes in ECs or the application of PFKFB3 inhibitors can indeed reduce the proliferation activity of tumor ECs." (PMID 33777937, 2021). "HIF-1 activation in tumor cells up-regulates the expression of some glycolytic enzymes and transporters, including 6-phosphofructo-2-kinase/fructose-2,6-biphosphatase 3 (PFKFB3), M2 isoform of pyruvate kinase (PKM2), and glucose transporter 1 and 3 (GLUT1, GLUT3)." (PMID 33430279, 2021). "It has been widely confirmed that PFKFB3 mediated tumor growth and angiogenesis." (PMID 34079757, 2021). "Phosphorylation of PFKFB3 S478 may be involved in regulating aerobic glycolysis, cell proliferation, cell migration, paclitaxel resistance, and tumor growth of BC cells in vivo." (PMID 33931981, 2021). "The expression of p-AKT, AKT and PFKFB3 in tumor tissues was also detected at the animal level, and we found that the expression of p-AKT and PFKFB3 was significantly decreased in the shRNA-TKTL1 group compared with the control group, which was consistent with the results of cell experiments." (PMID 34922556, 2021). "Therefore, we first investigated the impact of dual inhibition of VEGF and PFKFB3 on survival and tumor growth." (PMID 32641990, 2020). "Additionally, blocking PFKFB3 further reduced NF-κB signaling, invasion, metastasis, improved tumor perfusion and oxygenation by improving the integrity and stability of the vessels." (PMID 32012744, 2020). "Since tumour ECs (TECs) are highly glycolytic compared to normal proliferating ECs, one strategy is a blockade of glycolysis by inhibiting the glycolytic activator PFKFB3 with 3PO." (PMID 33092283, 2020). "In addition to its role in angiogenesis, PFKFB3 expression in tumour vasculature plays a role in metastasis dissemination by stimulating vascular permeability." (PMID 32911833, 2020).